PRL (prolactin)
Diseases named in the same sentence as PRL in open-access papers (continued):
Sharing a sentence is not in itself a finding about the gene and the disease.
psoriasis (14 papers, 2009 to 2025). An autoimmune condition characterized by red, well-delineated plaques with silvery scales that are usually on the extensor surfaces and scalp. "In psoriasis, elevated prolactin levels have been linked to an increase in keratinocyte proliferation—a hallmark feature of the disease." (PMID 39860587, 2025). "Various therapeutic approaches, including both topical and systemic treatments, have been associated with a notable decrease in serum PRL levels among patients undergoing psoriasis treatment." (PMID 41476991, 2025). "Previous studies have assessed the association of PRL levels with the severity of psoriasis; however, the results are contradictory." (PMID 24288511, 2013). "PRL appears to be implicated in the development of psoriasis and may serve as a biological marker for the disease’s activity." (PMID 41476991, 2025). "Elevated prolactin levels have been linked to an increase in keratinocyte proliferation and an increase in the expression of pro-inflammatory cytokines, and therefore lead to a worsening of psoriasis." (PMID 39860587, 2025). "Since pituitary PRL secretion may be regulated by IFNγ and TNFα, albeit in rodent studies, and since these cytokines and PRL have been implicated in the pathogenesis of psoriasis, we also examined whether these prototypic pro-inflammatory cytokines influence PRL and PRLR expression in the HF." (PMID 23626671, 2013). "It is now appreciated that PRL is an important regulator of human hair growth and may be implicated in the pathobiology of common, chronic skin diseases including psoriasis and lupus erythematosus." (PMID 23626671, 2013). "Understanding prolactin’s role in psoriasis underscores the need for therapies that modulate this hormone in patients who show elevated levels, especially during times of physiological stress or lactation." (PMID 39860587, 2025). "Prolactin can also stimulate lymphocyte activity, enhancing the immune response and potentially worsening psoriasis symptoms." (PMID 39860587, 2025). "This is consistent with the evidence from several studies that both local and systemic psoriasis treatments can reduce circulating PRL levels, correlating with treatment response." (PMID 39000207, 2024). "Future studies of the role of PRL in psoriasis need to simultaneously examine the effects and extent of circulating and intra-cutaneous production in addition to rigorously measuring stress, ideally in a suitably powered prospective study." (PMID 39000207, 2024). "Circulating prolactin levels were significantly higher among psoriasis patients, and a positive correlation with disease severity was identified." (PMID 38399624, 2024). "The fact that hormones play important roles in the pathogenesis of psoriasis is supported by a recent meta-analysis that evaluates the relationship between circulating prolactin levels and the severity of psoriasis." (PMID 38399624, 2024). "Studies in humans have also revealed a role of prolactin in the pathogenesis of certain skin pathologies, with significantly higher serum prolactin in patients with psoriasis, vitiligo and alopecia areata, when compared to controls." (PMID 31170219, 2019). "In the psoriasis group the mean prolactin level was reported as 365.05 mlU/L, with a range of 252 mlU/L to 459 mlU/L." (PMID 24707406, 2014). "We included AD patients since AD and psoriasis patients have some similarities and we wanted to assess if prolactin has a special role in psoriasis as compared to AD." (PMID 24707406, 2014). "In this study, we selected AD patients along with psoriasis patients in order to compare the serum level of prolactin in each group." (PMID 24707406, 2014). "Some studies indicate that elevated PRL levels may be present in patients with psoriasis and could contribute to worsening the condition." (PMID 41476991, 2025). "In conclusion, the connection between PRL and psoriasis is intricate and somewhat debated." (PMID 41476991, 2025).
psoriasis (continued). "Psoriasis treatment seems to have an impact on serum PRL levels." (PMID 41476991, 2025). "It is assumed that prolactin, a polypeptide hormone secreted by the anterior pituitary gland, stimulates the proliferation of keratinocytes, acts as an inductor of angiogenesis and promotes the infiltration of psoriasis lesions with Th1 cells." (PMID 38399624, 2024). "The results of our review indicate a link between sex hormones, prolactin and the hypothalamic–pituitary–adrenal axis with psoriasis severity and their modulation could improve psoriasis course." (PMID 38399624, 2024). "Ultimately a meta-analysis was required to conclusively answer whether serum PRL was elevated in psoriasis." (PMID 39000207, 2024). "In contrast, higher PRL levels have been reported in patients with psoriasis compared to control disease and healthy controls, and it has been suggested that PRL may play a role in the pathogenesis of psoriasis." (PMID 28690611, 2017). "As studying the etiology of psoriasis is receiving much attention nowadays and a quest for better treatment options is on the rise, this study was conducted in order to evaluate the role of prolactin in psoriasis and to compare its level between psoriatic and atopic patients." (PMID 24707406, 2014). "Recently, it has been reported that prolactin exerts a proliferative effect on human keratinocytes in vitro and may possibly play a role in the pathogenesis of psoriasis." (PMID 24707406, 2014). "Considering the proliferative effect of prolactin on human keratinocytes and given the fact that keratinocyte hyperproliferation is a dominant feature of psoriasis, it has been postulated that this hormone may play a role in the pathogenesis of the disease." (PMID 24707406, 2014). "However, studies with larger sample sizes are still necessary, to further study the role of prolactin in the pathogenesis of psoriasis." (PMID 24707406, 2014). "Prolactin has proliferative effects on human keratinocytes, a dominant feature of psoriasis, and it is thought that this hormone may play a role in the pathogenesis of the disease." (PMID 24707406, 2014). "Given the pro-inflammatory cutaneous cytokine milieu which is present in psoriasis, we speculated that cytokines, for example tumour necrosis factor alpha (TNFα) and interferon gamma (IFNγ), may up-regulate intracutaneous PRL production." (PMID 23626671, 2013). "Furthermore, according to our results, the only hormone that increases in psoriasis is PRL in male patients, which returns to the same level as healthy controls after treatment." (PMID 24288511, 2013). "In follow-up studies, the epidermal regulation of PRL and/or PRLR protein expression by TNF deserves to be characterized, since increased TNFα and PRL levels in psoriasis may both result in a decrease in PRLR expression." (PMID 23626671, 2013). "Existence of PRL receptors on epidermal keratinocytes provides more support for the hypothesis stating that PRL might have some role in the etiopathogenesis of psoriasis." (PMID 24288511, 2013). "PRL may play a significant role in the development of psoriasis by promoting several key processes." (PMID 41476991, 2025). "Thus, given PRL’s role as a stress hormone, it was reasonable to question whether PRL was a potential mediator of the effect of stress on psoriasis." (PMID 39000207, 2024). "In addition, circulating PRL in general, and skin-derived PRL in particular, may influence several key facets of psoriasis pathology." (PMID 39000207, 2024). "Moreover, the local tissue inflammatory milieu may also influence PRL expression, particularly in the context of psoriasis." (PMID 23626671, 2013). "In addition, some hormones may have role in pathogenesis of psoriasis due to their effects on keratinocytes proliferation; in vitro studies on prolactin (PRL) has demonstrated proliferative effect on keratinocytes, epithelial cells, and lymphocytes." (PMID 24288511, 2013).
psoriasis (continued). "Given the acute changes in PRL expression following stress exposure, the Trier Social Stress Test may offer a laboratory-controlled, standardised method to evaluate the role of PRL in the cutaneous response to stress and to determine whether this is dysregulated in patients with psoriasis." (PMID 39000207, 2024). "Yet, our study could not determine whether PRL had a causative role in psoriasis in males." (PMID 24288511, 2013). "Most recently, PRLR expression in the skin has been confirmed in lesional and non-lesional skin in patients with psoriasis and PRL expression is significantly expressed in lesional skin." (PMID 39000207, 2024). "Collectively, most of the evidence suggests that plasma PRL levels are on average not elevated in RA, while more validation is needed in conditions like psoriasis." (PMID 28690611, 2017). "In addition, we aimed to find a difference in prolactin, thyroid stimulating hormone (TSH), thyroid hormones (T3 and T4), and cortisol levels between patients with psoriasis and normal controls." (PMID 24288511, 2013). "The current serum-free human skin organ culture model permits one to investigate whether the regulation of PRL and/or PRLR is altered in inflammatory skin disorders, for example in psoriasis." (PMID 23626671, 2013).
TSHomas (14 papers, 2008 to 2025). "Alternatively, treatment with dopamine agonists, such as cabergoline, is an option, though it has been shown to be less effective than somatostatin analogs; the best results with dopamine agonists are observed in “mixed” TSHomas that also secrete prolactin." (PMID 40506885, 2025). "The more frequent cosecretion of GH and prolactin in TSHomas is due to their common origin in the PIT1 lineage." (PMID 37988667, 2023). "Mixed TSHomas account for 20%–25% of TSHomas, and approximately one in three co-secrete other anterior pituitary hormones, most commonly growth hormone (GH) and/or prolactin (PRL)." (PMID 36619586, 2022). "Indeed, a meta-analysis revealed 61% of the TSHomas to be monohormonal and 39% to be plurihormonal co-secreting GH (57.5%) and PRL (41.4%)." (PMID 36539773, 2022). "The majority of TSHomas (72%) secrete TSH alone, but 16% also secrete growth hormone (GH), 11% secrete prolactin (PRL), and 1% secretes LH or FSH." (PMID 18307779, 2008). "First, because of the lack of thyrotropinoma and gonadotropinoma patients in the center, we only included nonfunctioning, GH secreting, PRL secreting, and ACTH secreting PAs." (PMID 34765541, 2021). "And because no thyrotropinoma, and gonadotropinoma was treated in our center, the current study only included nonfunctioning, GH secreting, PRL secreting, and ACTH secreting PAs." (PMID 34136412, 2021).
viral infection (14 papers, 2014 to 2025). "PRL levels, varying by sex and life stage, may affect immune responses and susceptibility to viral infections." (PMID 41476991, 2025). "The cause of PPCM remains unknown; however, there are several theories, such as genetic predisposition, viral infections, and inhibition of angiogenesis and cardiotoxicity by truncated prolactin." (PMID 34725740, 2021). "Inflammatory cytokines such as IL‐1, IL‐2, and IL‐6 play a crucial role in promoting PRL production during viral infections." (PMID 41476991, 2025). "Acute viral infections trigger an increase in PRL levels through the stimulation of specific cytokines." (PMID 41476991, 2025). "The role of PRL in the pathophysiology of viral infections involves its participation in viral entry and replication processes, as well as the stimulation of PRL secretion through inflammatory signaling pathways." (PMID 41476991, 2025). "PRL has a complex relationship with viral disease severity, showing both proinflammatory and anti‐inflammatory effects across different viral infections." (PMID 41476991, 2025). "Overall, PRL is a complex hormone with significant implications for endocrine function, immune regulation, and immune responses to viral infections, highlighting the need for further research into its diverse roles in health and disease." (PMID 41476991, 2025). "The recent pandemic challenge of severe acute respiratory distress syndrome coronavirus type 2 (SARS-CoV-2) induced a plethora of studies concerning the mechanisms of this viral infection, with the role of PRL in the infection mechanisms among them." (PMID 36833950, 2023). "Viral infections with c-Fos activation showed that the Cg1 and PrL were similar in a similar state as during the activation of c-Fos neurons; however, the IL revealed a lower activation in c-Fos neurons under ChR2 photostimulation." (PMID 37113545, 2023). "PRL exhibits a dual role, possessing both proinflammatory and anti‐inflammatory properties, which positions it as a crucial factor in the pathophysiology of viral diseases." (PMID 41476991, 2025). "Viral infection treatments may benefit from PRL’s intricate immunological properties, as this hormone demonstrates nuanced potential for modulating immune responses and developing targeted therapeutic interventions." (PMID 41476991, 2025). "In summary, PRL significantly influences immune responses during viral infections." (PMID 41476991, 2025). "A deeper understanding of this relationship could lead to the development of therapeutic strategies aimed at modulating PRL’s effects on viral infections." (PMID 41476991, 2025). "PRL can modulate the activity of various immune cells, including T cells, B cells, natural killer cells, and macrophages, mounting an effective immune response against viral infections." (PMID 41476991, 2025). "The role of prolactin in viral infections has been priorly explored and seems to go hand in hand." (PMID 39595974, 2024). "The observed rise in circulating oestrogen and prolactin concentrations in SARS-CoV-2 positive patients may also suggest the endocrine-disrupting activity of the viral infection as a pathway of impairing male fertility." (PMID 39250513, 2024). "Other studies on PRL and virus infection concern chronic hepatitis C (HCV) infection." (PMID 36833950, 2023). "There might be a possible that the elevated expression of pro-inflammatory cytokines induced by virus infection may affect the PRL expression in vitro." (PMID 35910654, 2022). "Like the expression of PRL, viral infection also affects the expression of GH in plasma." (PMID 35910654, 2022).
viral infection (continued). "In our previous study, after virus infection, the levels of PRL and GH in plasma have changed and the increase PRL levels could reduce the expression of virus and pro-inflammatory factors in immune organs." (PMID 35910654, 2022). "Notably, PRL possesses anti‐inflammatory properties, suggesting that the increase in serum PRL levels during viral infections may serve as a compensatory response to counteract inflammation and restore homeostasis." (PMID 41476991, 2025). "Viral infections such as HIV can directly diminish dopaminergic tone, consequently leading to elevated PRL levels." (PMID 41476991, 2025). "In viral infections such as HIV, HCMV, HCV, and COVID‐19, PRL levels are often increased, which may influence the immune responses." (PMID 41476991, 2025). "Similarly to various viral diseases, such as HIV, HCV and CMV infection, the increased PRL levels are attributed to PRL’s role in viral entry and replication, as well as the induction of inflammatory-signaling pathways." (PMID 39595974, 2024). "Specifically, the Minister (Chen) herb significantly targets virus infection pathways and immune cell pathways, while the Adjuvant (Zuo) and Courier (Shi) herbs affected signaling regulation of oxidative stress (AGE–RAGE) and hormone secretion (Prolactin)." (PMID 31507421, 2019).
heart failure (13 papers, 2012 to 2025). Inability of the heart to pump blood at an adequate rate to meet tissue metabolic requirements. "We recently demonstrated beneficial effects associated with the prolactin release inhibitor bromocriptine at different doses when added to standard heart failure therapy in PPCM." (PMID 30121697, 2019). "However, our results suggested that the cause of hypoxia/ischemia by asphyxia compared with heart failure as the final condition is greatly related to the change in the CSF PRL concentration." (PMID 29949606, 2018). "Prolactin is a hormone that can regulate vessel formation and cardiac remodeling, which leads to defective cardiac angiogenesis, heart failure and subsequent mortality." (PMID 36394074, 2022). "We recently demonstrated in a multicenter, randomized controlled trial that treatment with the prolactin release inhibitor bromocriptine in addition to guideline-recommended heart failure therapy is safe and improves LV function and clinical outcome in PPCM." (PMID 30121697, 2019). "This trial will provide important knowledge on potential benefits and safety of prolonged inhibition of prolactin release with bromocriptine in addition to standard heart failure therapy in newly diagnosed PPCM." (PMID 26026286, 2015). "In contrast to most other studies on outcome in PPCM patients, a high percentage of patients in our cohort was treated with the Prolactin blocker bromocriptine in addition to standard treatment for heart failure." (PMID 23812247, 2013). "Several therapies have been proposed in PPCM in addition to conventional treatment for heart failure, including apheresis, intravenous gamma-globulin, immunomodulators, anti-viral agents, and particularly prolactin release inhibitors such as bromocriptine." (PMID 23251175, 2012). "Finally, it is the largest cohort treated with the novel disease specific therapy concept using the Prolactin blocker bromocriptine in addition to the standard therapy for heart failure aiming to block potential adverse effects of the angiostatic 16 kDa Prolactin." (PMID 23812247, 2013). "Recently, it has been hypothesized that addition of bromocriptine or other inhibitors of prolactin release to standard therapy may be effective in favoring both clinical status and LV function, and in preventing chronicization of heart failure in subjects with PPCM." (PMID 23251175, 2012). "However, the particular role of prolactin in heart failure in particular has not been fully understood." (PMID 33396861, 2020).